ASXL1 (ASXL transcriptional regulator 1)
Diseases named in the same sentence as ASXL1 in open-access papers (continued):
Sharing a sentence is not in itself a finding about the gene and the disease.
Bohring-Opitz syndrome (continued). "They found that some patients with clinical manifestations resembling those of Bohring-Opitz syndrome (BOS), which is associated with de novo truncating or missense mutations in the ASXL1 gene, actually had abnormalities in the ASXL3 gene rather than ASXL1 mutations." (PMID 36699804, 2022). "Bohring-Opitz syndrome (BOS) is a severe congenital disorder associated with de novo mutations in the Additional sex combs-like 1 (ASXL1) gene, characterized by symptoms that include developmental delay and musculoskeletal and neurological features." (PMID 31006630, 2019). "Thus, the present case might be considered as an example of nonmutated ASXL1 loss, which is likely to be associated with milder phenotypes of Bohring-Opitz syndrome." (PMID 23476833, 2013).
myeloid leukemia (16 papers, 2015 to 2026). A clonal proliferation of myeloid cells and their precursors in the bone marrow, peripheral blood, and spleen. "In the context of myeloid leukemia, mutations in ASXL1 have been shown to lead to the loss of ASXL1 expression and a consequent reduction of PRC2-mediated histone 3 lysine 27 tri-methylation (H3K27me3), a histone modification associated with gene repression." (PMID 39614348, 2024). "Most of the studies on human ASXL1 function are in the context of myeloid leukemia and propose that truncating ASXL1 mutations result in haploinsufficiency, dominant-negative, or gain-of-function effects." (PMID 37053013, 2023). "Loss of Polycomb silencing is also observed in some ASXL1 mutant myeloid leukemias, further supporting this model." (PMID 34186021, 2021). "MEG-01 and TS9;22 are other myeloid leukemia cell lines with ASXL1 mutations (G646WfsX12 in MEG-01 and R693X in TS9;22)." (PMID 30013160, 2018). "Although these studies have clearly shown a tumor suppressor role for BAP1, several lines of evidence also raise the possibility that BAP1 activity drives the growth of myeloid leukemia cells with ASXL1 mutations." (PMID 30013160, 2018). "It has been shown that enforced expression of wild-type ASXL1 in myeloid leukemia cell lines with homozygous nonsense ASXL1 mutations resulted in growth suppression." (PMID 26623729, 2015). "Homozygous nonsense ASXL1 mutations have been shown to result in loss of ASXL1 protein expression in myeloid leukemia cells." (PMID 26623729, 2015). "Heterozygous mutations of ASXL1 that result in premature truncations are frequent in myeloid leukemias and Bohring–Opitz syndrome." (PMID 26095772, 2015). "The ASXL1 gene is involved in histone modification and chromatin remodeling, and heterozygous mutations in this gene can lead to premature truncations, potentially resulting in myeloid leukemia and Bohring–Opitz syndrome." (PMID 38256178, 2024). "Heterozygous mutations of ASXL1 are frequent in myeloid leukemias and other malignancies." (PMID 32010606, 2019). "Thus, BAP1 has a growth-promoting effect in a wide range of myeloid leukemia cells, including AMLs with ASXL1 mutations or MLL-fusions." (PMID 30013160, 2018). "Although ASXL1 mutations are frequently found in human diseases, including myeloid leukemia, the cell proliferation–associated function of ASXL1 is largely unknown." (PMID 28701722, 2017). "The human myeloid leukemia cell line KBM5 (derived from a CML patient in blast phase) was chosen for this study as it lacks wild-type ASXL1 protein expression, due to a homozygous point mutation (c.2128G > T, p.G710X) in the ASXL1 gene that creates a premature termination codon." (PMID 26623729, 2015). "Variants in ASXL1 can disrupt this equilibrium, favoring a stem-cell identity over differentiation in both BOS and myeloid leukemias." (PMID 39614348, 2024). "This multiomics approach identifies the core impact of ASXL1 mutations and therapeutic targets for BOS and myeloid leukemias." (PMID 37053013, 2023). "In regards to the regulation of the posterior HOXA cluster by ASXL1, there is one proposed mechanism from a study in ASXL1-/- myeloid leukemia cells, which showed global depletion of H3K27me3 and EZH2 at the posterior HOXA cluster." (PMID 35361921, 2022). "A variety of other factors frequently aberrant in myeloid leukemia can affect PRC2 function and disease pathogenesis, including Additional Sex Combs Like 1 (ASXL1) and splicing gene mutations." (PMID 32650416, 2020). "Premature truncations of ASXL1, a subunit of a deubiquitinase complex, are frequent in myeloid leukemia." (PMID 26095772, 2015). "Hhex expression, in combination with a mutant form of additional sex combs-like 1 (Asxl1) an epigenetic modulator often mutated in myeloid leukaemia, was also found to enhance Runx1-ETO and Flt3-ITD-driven myeloid leukaemia via upregulation of Myb and Etv5 in mice." (PMID 37398663, 2023).
myeloid leukemia (continued). "Our ChIP data following co-expression of ASXL1 and RUNX1 mutations recognized the deregulation of ID1 in myeloid leukemia cells, suggesting the role of myeloid leukemia transformation by combined mutations were at least partly attributed to the upregulated ID1 expression." (PMID 31640815, 2019). "Importantly, BAP1 depletion inhibits posterior HOXA gene expression and leukaemogenicity of ASXL1-MT-expressing myeloid leukemia cells." (PMID 30013160, 2018). "Importantly, Bap1 depletion using CRISPR/Cas9 substantially inhibits the leukaemogenicity of myeloid leukemia cells expressing mutant ASXL1." (PMID 30013160, 2018). "Notably, the leukemic cells from our patients harboring coexisted mutations of ASXL1 and RUNX1 correlated with the upregulation of ID1 gene expression, supporting the role of cooperative mutation of ASXL1 and RUNX1 on ID1 expression and myeloid leukemia transformation." (PMID 31640815, 2019). "BAP1 knockdown across multiple myeloid leukemia cell lines selectively decreased HLA-E and IFN-γ-R1 expression in ASXL1-mutant backgrounds." (PMID 42295372, 2026).
Thrombocytopenia (15 papers, 2017 to 2025). A reduction in the number of circulating thrombocytes. "Our results indicated a higher incidence of ASXL1 mutation in the PROG group than in the non-thrombocytopenia group, which corresponds to the findings of a previous study on cytopenic-phenotype MF." (PMID 39574914, 2024). "Multivariate analysis indicated that progression to thrombocytopenia and ASXL1 and IDH1 mutations were associated with poor overall survival." (PMID 39574914, 2024). "In the pre-PMF group, we found that thrombocytopenia, ASXL1, MPL, U2AF1, SETBP1, and SRSF2 mutations were associated with inferior overall survival." (PMID 36139644, 2022). "In univariate analysis, survival was detrimentally impacted by the presence ASXL1 mutations, thrombocytopenia, and increased total bilirubin." (PMID 29440636, 2018). "The multivariate analysis revealed that progression to thrombocytopenia (p = 0.042, hazard ratio (HR) = 7.7, 95% confidence interval (CI) = 1.04–7.70), ASXL1 mutation (p = 0.041, HR = 9.91, 95% CI = 1.05–9.91), and IDH1 mutation (p = 0.02, HR = 75.6, 95% CI = 5.19–1103) were associated with poor OS." (PMID 39574914, 2024). "However, on multivariable analysis, only the presence of ASXL1 mutations and thrombocytopenia remained independently adverse prognostic factors of decreased survival." (PMID 29440636, 2018). "We identified ASXL1 mutation and low CD45RA+CD4+ T-cell prevalence as potential aggravators of thrombocytopenia." (PMID 39574914, 2024). "ASXL1 mutation and low CD45RA+CD4+ T-cell counts correlated with progression to thrombocytopenia." (PMID 39574914, 2024). "In our case, ASXL1 mutation (along with thrombocytopenia) was detected with PRKDC and MYOM2 mutations without the sequencing panel at preliminary diagnosis at low levels, and VAF of CSF3RT618I, SETBP1, and SRSF2 increased at progression to AML transformation." (PMID 33822276, 2021).
chronic myeloid leukemia (12 papers, 2015 to 2025). "Atypical chronic myeloid leukemia (aCML) is most known for granulocytosis with marked dysplasia and often harbors ASXL1 mutations, but SETBP1 and ETNK1 are more specific to this disease." (PMID 35844680, 2021). "We were the first to report that mutations of ASXL1 occur in chronic myeloid leukemia (CML), and ASXL1 mutations have been associated with disease progression and blast crisis in CML." (PMID 26623729, 2015). "For example, pathogenic or likely pathogenic alleles in GATA2, ASXL1, or TET2 were found in 10% of pediatric chronic myeloid leukemia cases, with additional putative risk alleles in another 60%." (PMID 41010648, 2025). "Previously, we observed that transcription factor RUNX1 mutations (RUNX1-MT) coexisted with ASXL1-MT in CMML and at myeloid blast phase of chronic myeloid leukemia." (PMID 31640815, 2019).
colorectal cancer (12 papers, 2013 to 2025). A primary or metastatic malignant neoplasm that affects the colon or rectum. "This mutation is almost restricted to the haematopoietic lineage with the notable exception of MSI-high colorectal cancer cell lines where ASXL1 mutations have been associated with microsatellite instability and predicted NMD (nonsense mediated decay) resistant derived neoantigens." (PMID 30222780, 2018). "For example, a 3-mm TA harbored one of the highest MB of 6.45, with pathogenic mutational defects in numerous colorectal cancer driver genes (e.g., APC, SOX9, TCF7L2, ASXL1, ERBB3, MAP2K1, and PTPRS)." (PMID 40757636, 2025). "Predictions of known cancer driver genes in new cancer types include SPTA1, CHD4 and ASXL1 in colorectal cancer, FOXO3, MUC16 and ZFPM1 in breast cancers and CNTNAP2, CTNND2 and TRRAP in lung adenocarcinoma." (PMID 38890488, 2024). "In another study found that circITGA7 sponges miR-3187-3p to upregulate ASXL1, suppressing colorectal cancer proliferation." (PMID 36059637, 2022). "For instance, circITGA7 hampered the progression of colorectal cancer through sponging miR-3187-3p, thus elevating ASXL1 level." (PMID 33526034, 2021). "ASXL1 is over-expressed in 88.9% of 20q11.21 amplified colorectal cancers in the TCGA cohort, while POFUT1 is over-expressed in 90.5% of 20q11.21 amplified cases in the same cohort." (PMID 34577783, 2021). "For example, circRNA ITGA7 regulated colorectal cancer proliferation by sponging miR-3187-3p to elevate ASXL1 expression." (PMID 32714095, 2020). "However, ASXL1 amplifications appear to be reasonably common in solid tumors and are present in >20% of uterine carcinosarcomas and ∼10% of colorectal cancers, according to TCGA data." (PMID 28835367, 2017). "Gain of ASXL1, also located on 20q11.21, thought to be a tumor suppressor, is associated with a favorable prognosis; patients with ASXL1 gain had a mean survival time of 48 months, significantly longer than 41 months in patients with ASXL1 negative colorectal cancer." (PMID 35565354, 2022). "Over-expression of amplified genes is partially overlapping with the over-expression of the genes in 20q11.21 amplified clinical samples of colorectal cancer patients, where POFUT1 but also ASXL1, and, in fewer cases, KIF3B and TPX2, are often over-expressed." (PMID 34577783, 2021).
primary myelofibrosis (11 papers, 2015 to 2026). Myelofibrosis with myeloid metaplasia is a myeloproliferative disease with annual incidence of approximately 1 case per 100,000 individuals and age at diagnosis around 60 (an increased prevalence is noted in Ashkenazi Jews). "Based on bone marrow morphology, biopsy (revealing Grade MF-2 fibrosis), and molecular testing (detecting a JAK2 V617F mutation with a variant allele frequency of 44.67% and an ASXL1 mutation), a diagnosis of primary myelofibrosis (PMF) was established." (PMID 41988126, 2026). "Additional sex combs like 1 (ASXL1) mutations are one of the most common molecular biological abnormalities in patients with primary myelofibrosis (PMF), and the effect of these mutations on prognosis remains controversial." (PMID 33386934, 2021). "Guglielmelli, Coltro, and investigators reported in 2022 an analysis of 523 patients with MF at various disease stages, including primary myelofibrosis (PMF), pre-MF, and post-polycythemia vera (PPV-MF), in which ASXL1 mutations were identified in 157 (30%) of patients." (PMID 37760623, 2023). "Like ASXL1, it was also explored by Guglielmelli in 2011 in an analysis of 370 patients with primary myelofibrosis and 148 with post-PV/post-ET MF, where genotyping for EZH2 identified mutations in 5.9%, 1.2%, and 9.4% of patients with primary MF, post-PV MF and post-ET MF, respectively." (PMID 37760623, 2023). "Thirteen genes including ASXL1, U2AF1, SRSF2, SF3B1, and ZRSR2 had significantly higher mutation frequencies in primary myelofibrosis (PMF) compared with essential thrombocythemia and polycythemia vera; this difference distinguished PMF from MPN and likened it to MDS." (PMID 33117717, 2020). "Gene mutations in epigenetic regulators (ASXL1, TET2, DNMT3A and EZH2) and RNA splicing (U2AF1 and SRSF2) were considered as the additional subclonal mutations and cooperated with the MPN driver mutation (JAK2, MPL or CALR) to play a key role in the pathogenesis of primary myelofibrosis." (PMID 35740649, 2022).
breast carcinoma (10 papers, 2017 to 2024). "Thus, functional roles of ASXL1 might be altered by gene amplification or gain-of-function mutations in a set of breast cancer." (PMID 28055972, 2017). "Similar to ASXL1, KMT2C mutation was also enriched in late-stage or metastatic status of iCCA, breast cancer, and prostate cancer and was associated to poor prognosis." (PMID 32010606, 2019). "In this study, we also found that ASXL1 gene, localized at 20q11 region, is commonly amplified/gained in breast cancer." (PMID 28055972, 2017). "Previous investigations had reported that TSC2, ARID1A, AXIN1, CASP8, CDH1, and ASXL1 could play roles in tumor suppression in diverse cancer types, including breast cancer." (PMID 29414922, 2018). "Here, we focused on analyzing the mutation spectrum of ASXL1-3 and CHD3-5 genes in breast cancer." (PMID 28055972, 2017). "ASXL1 (Additional sex comb like 1) is a TSG involved mainly in hematological cancers, but also in other malignant processes such as breast cancer and prostate cancer." (PMID 33672345, 2021).
atherosclerosis (8 papers, 2020 to 2025). A disease characterized by the build-up of fatty material and calcium deposition in the arterial wall resulting in partial or complete occlusion of the arterial lumen. "The mechanisms for how ASXL1 (additional sex combs-like 1) mutations lead to inflammation and atherosclerosis have only recently been elucidated." (PMID 39988580, 2025). "ASXL1 mutation is prevalent in atherosclerosis/chronic ischemic heart-failure-affected individuals." (PMID 37626784, 2023). "Although AIM2 inflammasome activation has been shown to be sufficient to promote atherosclerosis in Jak2 CH, our findings suggest that other pathways may also contribute to ASXL1-mediated CVD risk." (PMID 37498674, 2023). "Furthermore, the relationship between ASXL1 mutations and inflammation or atherosclerosis remains poorly understood, though it is hypothesized that the myeloid bias seen in ASXL1 CHIP carriers may produce effects similar to those seen with TET2 loss-of-function mutations." (PMID 39997650, 2025). "In contrast to TET2 and DNMT3A, where NLRP3 inflammasome activation appears predominant as a mechanism that drives accelerated atherosclerosis, recent data suggest that ASXL1 and JAK2 CHIP provoke activation of the AIM2 inflammasome." (PMID 39352379, 2024). "Although the clinical significance of LAB CH in atherosclerosis needs to be further clarified, inflammasome activation is prominent in TET2, JAK2VF, and probably ASXL1 CH, suggesting that common underlying mechanisms may support inflammatory crosstalk." (PMID 39531316, 2024). "The role of ASXL1 in atherosclerosis remains largely unknown and EIF2 downregulation promotes atherosclerosis, indicating that ASXL1 and EIF2 may play novel roles in hemodynamics-mediated EC efferocytosis, which needs to be further validated." (PMID 38646649, 2024). "We set out to model Asxl1 CH in vivo and monitor atherosclerosis." (PMID 37498674, 2023). "Yet, in line with other studies, we found that introducing Asxl1 mutations via bone marrow transplantation in mice did not confer a clonal advantage or lead to the development of atherosclerosis within a short time frame." (PMID 37498674, 2023). "Like ASXL1, JAK2 VF CHIP also drives atherosclerosis by activating the AIM2 inflammasome." (PMID 39352379, 2024). "So far, murine models of ASXL1 CHIP have not shown increased atherosclerosis." (PMID 39352379, 2024). "Our current observations are consistent with previous reports showing impaired initial HSC proliferation and clonal expansion in Asxl1 CHIP mice and suggest that a much longer follow-up time (>1 year) may be needed to promote atherosclerosis development in the Asxl1 mouse model." (PMID 37498674, 2023).
Thrombocytosis (8 papers, 2021 to 2025). Increased numbers of platelets in the peripheral blood. "As far as their biologic significance, ASXL1 mutation is recognized within the so-called CHIP, as early initiator of a clonal expansion and as favoring a state of thrombocytosis." (PMID 33791220, 2021). "It has been demonstrated that transgenic expression of mutant Asxl1 could lead to thrombocytosis, age-related anemia, and myeloid dysplasia." (PMID 34502524, 2021). "Among the CH mutations, genes encoding Additional sex combs like 1 (ASXL1), Splicing factor 3B subunit 1 (SF3B1), DNA methyltransferase 3a (DNMT3A), Src homology 2 B3 (SH2B3, also named LNK), and JAK2 are considered to be associated with thrombocytosis and/or platelet hyper-reactivity." (PMID 34502524, 2021).
thrombosis (8 papers, 2017 to 2025). "Several lines of evidence indicate that mutations in JAK2, MPL, TET2 and ASXL1 gene and polymorphisms in several clotting factors (GPIa, GPIIa, and GPIIIa) are associated with the occurrence and prevalence of thrombosis in MPN patients." (PMID 36611455, 2023). "In an age-matched case–control study of PV patients, investigators observed that the presence of ≥1 TET2 or ASXL1 or DNMT3A mutations significantly increased the risk of thrombosis, and that PV patients with a TET2 mutation had a significantly higher risk of thrombosis." (PMID 36431092, 2022). "Age greater than 60 years, the presence of the cardiovascular risk factors, mutation for thrombosis (DNMT3A, ASXL1, or BCOR/BCORL1), and previous thrombosis made part of this score." (PMID 41153823, 2025). "Among patients with variations associated with CHIP (DNMT3A, TET2, ASXL1, JAK2), thrombosis occurred in 5 patients (62%; odds ratio [OR], 5.6; 95% CI, 1.3-15.9) and death in 3 patients (37%; OR, 6.1; 95% CI, 1.3-26.9)." (PMID 34357393, 2021). "Additionally, the non-driver TET2 and ASXL1 mutations did not impact arterial nor venous thrombosis." (PMID 29282357, 2017). "TET2 or ASXL1 mutations did not impact arterial nor venous thrombosis." (PMID 29282357, 2017). "Our study also showed that previous thrombotic history and NLR were independent risk factors for thrombosis in PV patients, and that TET2 or ASXL1 did not affect thrombosis in PV patients, even in the univariate analysis." (PMID 36431092, 2022).